Y_RNA (Y RNA )
Gene: Miscellaneous RNA gene on chromosome 5 (179,847,035 to 179,847,130, reverse strand). Ensembl gene ENSG00000252202.
Homologues: Orthologues: chimpanzee Y_RNA (98% identical), macaque Y_RNA (84% identical). Paralogues in human: RNY4P3 (88% identical), Y_RNA (86% identical), RNY4 (85% identical), RNY4P7 (85% identical), Y_RNA (85% identical), RNY4P10 (83% identical), RNY4P14 (83% identical), RNY4P25 (83% identical), RNY4P36 (83% identical), RNY4P6 (83% identical), Y_RNA (83% identical), RNY4P19 (82% identical), and 92 more.